INS (insulin)
Diseases named in the same sentence as INS in open-access papers (continued):
Sharing a sentence is not in itself a finding about the gene and the disease.
diabetes (continued). "Indeed, these GTPases are important components regulating the final events of insulin exocytosis, such as granule docking and functional defects involving them could play a role in the development of metabolic diseases such as diabetes." (PMID 23826383, 2013). "Diabetes mellitus is an endocrine disease characterised by chronic hyperglycaemia with the disturbance of carbohydrate, fat and protein metabolism resulting from defects in insulin secretion, insulin action or both, and is typically associated with the failure of pancreatic β-cells." (PMID 23641947, 2013). "Diabetes mellitus (DM) is a disease that consists of ineffective insulin regulation leading to derangements in carbohydrate, protein, and fat metabolism." (PMID 23691264, 2013). "Thus, while lower doses of 20–25 mg/kg STZ were sufficient to elevate blood glucose levels without impairing insulin secretion, the higher dose of STZ caused severe diabetes, as shown by increased glucose, β-OHB, triglycerides and decreased insulin concentrations." (PMID 24063408, 2013). "Deficiency of hepatic GCK activity is unlikely to be caused by mutations that inactivate the entire GCK gene as insulin secretion is not lost in these species and they do not exhibit the symptoms of diabetes that are seen when GCK is depleted from pancreatic islets of mice." (PMID 23573289, 2013). "Moreover, depression may also results from the burden of living with T2DM such as poor diet, physical inactivity and taking insulin or from the psychological stress while coping with diabetes." (PMID 23968401, 2013). "Furthermore, the adiponectin-secreting and insulin-sensitizing properties of F. deltoidea indicated that this plant could ameliorate systemic insulin resistance and may potentially be beneficial for type 2 diabetes mellitus related to insulin resistance." (PMID 22701507, 2012). "Therefore, it seems reasonable to hypothesize that sporadic AD represents a form of diabetes that selectively involves the brain and has the disturbed insulin signaling pathway in common with type 1 and type 2 diabetes mellitus." (PMID 22403710, 2012). "Thus, the inactivation of PDC that occurs in most of the major tissues of the body during starvation and diabetes is likely explained by the effects that a decrease in insulin and an increase in glucocorticoids and FFAs have on PDK4 expression under these conditions." (PMID 23730261, 2012). "Diabetes mellitus (DM) is a metabolic disorder characterized by hyperglycemia resulting from defects in insulin secretion, insulin action or both." (PMID 22867128, 2012). "Interestingly, they also found that insulin-sensitive individuals who developed diabetes during 7-years of follow-up had a CVD risk similar to people who did not develop diabetes." (PMID 22720085, 2012). "Diabetic retinopathy (DR) is a progressive and long-term microvascular complication of diabetes mellitus (DM) defined by defects in insulin metabolism and dysfunction in carbohydrate, lipid and protein metabolism." (PMID 23226496, 2012). "Type 2 diabetes mellitus (DM) is characterized by impaired insulin secretion from pancreatic β-cells." (PMID 21785581, 2012). "Moreover, it was reported that in ob/ob mice in which miR-375 was deleted, they develop a marked decrease in beta-cell mass, which results in a severe insulin-deficient diabetes not found in ob/ob mice." (PMID 22577380, 2012). "Formulated from an engineering point of view, the control of diabetes is driven by routine self-treatment behaviors which may occasionally evolve into hypo- or hyperglycemia-triggering events, for example, insulin mistiming, bolus/basal imbalance, missed meal, or excessive exercise." (PMID 24278682, 2012). "We propose that given the higher random insulin levels and better glucose clearance in Wdr13 knockout mice, this protein may be explored as a potential candidate drug target for ameliorating impaired glucose metabolism in diabetes." (PMID 22715406, 2012).
diabetes (continued). "Hyperinsulinemia has been widely proposed as a predisposing factor for stent restenosis in diabetic patients, and concerns have been raised over the management of diabetes with exogenously administered insulin, as it may accelerate progression of CAD through its atherogenic mechanisms." (PMID 22805289, 2012). "Type II diabetes mellitus (DM) is a metabolic disorder characterized by hyperglycemia and insufficiency of secretion or action of endogenous insulin." (PMID 23843827, 2012). "Lack of Cdk4 expression in mice leads to insulin-deficient diabetes." (PMID 22675349, 2012). "Similarly, subjects with normal glucose tolerance, impaired glucose tolerance, mild diabetes or type 2 diabetes mellitus were reported to exhibit markedly lower serum/plasma concentrations of glucose, insulin and C-peptide after honey supplementation than after dextrose, sucrose or simulated honey." (PMID 22337138, 2012). "Our findings implied that since Mlx was a differentially upregulated gene and the putative target of multiple downregulated miRNAs, it may play an important regulatory role in the “insulin regulation and diabetes” module—a prediction that is supported by recent reports." (PMID 22629440, 2012). "More than half were treated with insulin and most had had DM for 4-9 years (median 8 years), with about one third reporting diabetes-related complications." (PMID 23396799, 2012). "Moreover, exclusion of type 1 diabetes patients based on insulin use or age at diabetes diagnosis, did not weaken the associations." (PMID 22927948, 2012). "Another possible explanation for the association of insulin use with the prevalence of DPN in this cohort could be that insulin use indicates beta cell failure in this group of patients and may reflect a later stage in the natural history of diabetes or a greater severity." (PMID 22642973, 2012). "Therefore, we can suggest that the abnormal insulin signaling observed in wounded skin of diabetic rats might contribute to the impaired wound healing observed as a complication of diabetes." (PMID 22662132, 2012). "Diabetes mellitus (DM) is a chronic disease derived from the inadequate production of insulin in the pancreas or from the ineffective use of available insulin." (PMID 22714855, 2012). "Decreased insulin sensitivity that occurs during puberty, particularly in females, and psychosocial factors, such as the level of adjustment to illness, may play an additional role in sustained poor diabetes management." (PMID 22672865, 2012). "This may explain the inability of GIP to induce insulin secretion in diabetes." (PMID 22973260, 2012). "While increased fractional excretion of Mg at elevated insulin concentrations may be at play in both MetS and T2DM, mechanisms for Mg loss specific to diabetes, such as renal Mg wasting secondary to osmotic diuresis during glucosuria, might be associated with comparatively greater reductions in sMg." (PMID 22405520, 2012). "Thus, besides its well-known role in longevity, insulin may constitute a promising therapy against diabetes- and age-related neurodegenerative disorders." (PMID 22500228, 2012). "Moreover, the β-cell-specific VEGF-A deficient mouse showed the altered insulin secretion despite maintaining normal β-cell mass and the lost of capacity to induce expansion of β-cell mass after STZ-induced diabetes followed by bone marrow transplantation compared with the wild-type mouse." (PMID 22879915, 2012). "These agents have been investigated widely as an adjunct to therapy in diabetes as they offer an obvious alternative to insulin, but their metabolic effect could also be extended to the heart as they can enable the heart to switch to the more energy-efficient glucose-dependent pathway." (PMID 22811735, 2012). "In addition, higher magnesium intake has been shown to be associated with lower fasting insulin concentrations among women without diabetes." (PMID 22415230, 2012).
diabetes (continued). "Whereas type 1 diabetes mellitus results from selective destruction of the insulin- producing beta cells of the pancreas, type 2 diabetes is primarily characterized by insulin resistance followed by progressive beta-cell dysfunction, resulting in low insulin levels in the long term." (PMID 22621761, 2012). "As for pancreatic cancer, undiagnosed neoplastic proliferation, leading to impaired insulin secretion, could facilitate the development of hyperglycemia; in this case, diabetes could be the first clinical manifestation of cancer, thus producing the reported epidemiological association." (PMID 23209929, 2012). "The World Health Organization (WHO) defines diabetes as a metabolic disorder of multiple etiologies characterized by chronic hyperglycemia with disturbances of carbohydrate, fat, and protein metabolism that results from defects in insulin secretion, insulin action, or both." (PMID 22851968, 2012). "However, non-obese diabetes patients have a more deficient insulin secretion and less peripheral insulin resistance as compared to obese diabetes patients indicating a different cause of hyperglycemia." (PMID 22927948, 2012). "In conclusion, the alteration in CAF tests, level of insulin, oxidative stress, inflammatory response, lipid profile and coronary atherogenic lipid risk factors in IFG group indicate their higher risk for conversion to diabetes, development of atherosclerosis and cardiovascular diseases in future." (PMID 22860025, 2012). "In the case of diabetes, younger children may need a great deal of parental involvement in the physical aspects of caring for their diabetes (e.g., giving shots, drawing up insulin), whereas older children may need verbal prompts and cues to facilitate self-management behaviors." (PMID 23174044, 2012). "Another attractive feature of the metabolic/brain insulin resistance hypothesis is that it demystifies the pathophysiology of AD by relating it to other well-recognized systemic diseases, i.e. diabetes mellitus, non-alcoholic steatohepatitis, and metabolic syndrome." (PMID 22329651, 2012). "The major types of diabetes mellitus are type 1 and type 2, the former arising from inadequate production of insulin due to pancreatic β-cell dysfunction, and the latter from reduced sensitivity to insulin in the target tissues and/or inadequate insulin secretion." (PMID 23044503, 2012). "Also worthy of consideration is that the introduction of insulin self-injection pens for patients with diabetes led to an improvement in patient compliance and treatment outcomes, with patients reporting that they found injection pens less painful than syringes and needles." (PMID 23167906, 2012). "Moreover, after surgery, they could observe a significant decrease of apelin levels only in the morbidly obese subjects with impaired fasting glucose or diabetes, a decrease that followed the changes in blood glucose and insulin sensitivity." (PMID 23227256, 2012). "IDE is closely related to diabetes mellitus (DM) and Alzheimer’s disease (AD), because insulin and Aβ play critical roles in the pathogenesis of DM and AD, respectively." (PMID 22870279, 2012). "Diabetes mellitus (DM) is a chronic and life threatening disease that is induced because of low production of insulin or insensitivity to this substance." (PMID 24757604, 2012). "It is possible that fitness may improve risk factors associated with heart disease (cholesterol and blood pressure), but not those associated with diabetes (insulin)." (PMID 22693553, 2012). "Therefore, a proposed integration of the public and private healthcare systems may help to make diabetes care, including insulin initiation delivery, more effective and efficient." (PMID 22545648, 2012). "In addition, O. stamineus extract also potentiated glucose-induced insulin secretion may be beneficial to patients with diabetes mellitus who have a defect in the insulinotropic response to glucose." (PMID 23039079, 2012).
diabetes (continued). "However, as we measured plasma adiponectin as a biomarker and not glucose or insulin and our trial only lasted for six months, additional research is needed to characterize fully the role of Se in diabetes risk." (PMID 23028897, 2012). "This hypothesis is supported by the downregulation of neuronal insulin signaling pathways and brain glycolytic enzymes in uncontrolled diabetes (probably due to the inhibition of IR phosphorylation) that may culminate in progressive impairment in learning, memory, and cognition." (PMID 22500228, 2012). "Diabetes mellitus (DM) is a chronic degenerative disease that impairs normal insulin production and use." (PMID 22714855, 2012). "Thus, nasal exposure to insulin induces CD8+γδ T cells capable of suppressing diabetes development in mice, anti-γδ antibody disrupts oral mucosal tolerance to ovalbumin in mice, and oral administration of antigen does not induce tolerance in TCRδ-knockout mice." (PMID 22428018, 2012). "This must be distinguished from the secondary effect of hunger resulting from hypoglycaemia that may follow the exogenous administration of insulin (the associated overcompensatory eating may provide some explanation as to why patients with diabetes treated with insulin tend to gain weight)." (PMID 22719753, 2012). "Also, diabetes-like symptoms may occur in rapamycin-treated mice and animals with genetically inhibited insulin/IGFI signaling." (PMID 22683661, 2012). "Moreover, among those receiving insulin therapy, regimen adherence, persistence and intensity may be poor, resulting in worse glucose control and increased hospital admissions for diabetes complications." (PMID 22313123, 2012). "Diabetes mellitus (DM) is a group of metabolic disorders characterized by the presence of a chronic hyperglycemia due to defective insulin secretion and/or insulin action." (PMID 22967092, 2012). "But there are two possibilities; the first possibility might be in association with increased vulnerability of diabetic patients for HCV as a result of repeated exposure for finger prick injury, daily insulin injection and immune compromised state as result of diabetes." (PMID 23049551, 2012). "Understanding how insulin signaling alters the intracellular trafficking of GLUT4 as well as understanding the fate of glucose transported into the cell by GLUT4 will be critically important for seeking solutions to the current rise in diabetes and metabolic disease." (PMID 27335671, 2012). "Increased secretion of insulin may temporarily compensate for these alterations, but the chronic presence of triggering mechanisms may lead to dysfunction of these cells, thereby promoting diabetes." (PMID 23241342, 2012). "Two different models of diabetes were used: one with similarities to T1D (alloxan-treatment) in which mice were severely hyperglycemic and insulin deficient, whereas T2D was induced by HFD which resulted in moderate hyperglycemia with increased serum insulin concentrations." (PMID 21799868, 2011). "However, in the context of excess caloric intake, low GH leads to impaired insulin output, and thereby could contribute to the development of diabetes." (PMID 21283519, 2011). "Objectives of the study reported here were to identify values for measurement of HbA1c percentage in blood samples obtained from NHPs (Macaca fascicularis) to determine whether these percentages varied with respect to glycemic control after diabetes induction and insulin treatment." (PMID 21559266, 2011). "Diabetes Mellitus (DM) is a serious metabolic disorder, characterized by defects in both insulin secretion and action." (PMID 21533139, 2011). "However, the obese and hyperproinsulinemic Pc1N222D/N222D mutant mice, which have a mutation in the highly conserved codon 222 localized to the catalytic domain of PC1/3, escape diabetes by β-cell expansion and increased secretion of a less active form of insulin due to improper insulin processing." (PMID 21935364, 2011).
diabetes (continued). "Moreover, rare CEL gene defects in this region are responsible for a monogenically derived diabetes condition called maturity-onset diabetes of the young type 8 (MODY8), also known as diabetes and pancreatic exocrine dysfunction (DPED), which causes a defect in insulin secretion." (PMID 22162806, 2011). "Thus, ozone administration in diabetes mellitus rats reduced levels of oxidative stress markers and improved renal antioxidant enzyme activities, especially when rats were treated with a combination of ozone and insulin." (PMID 22185664, 2011). "Individuals with a genetic predisposition to Type 2 diabetes again showed a reduced insulin sensitivity as well as a more pro-atherogenic profile when compared to the individuals lacking heredity for diabetes (larger waist circumference, lower HDL-cholesterol, higher Apo B and Apo B/Apo A1 ratios)." (PMID 21532749, 2011). "Diabetes mellitus (DM) is a group of metabolic diseases characterized by hyperglycemia resulting from the defects in insulin secretion, insulin action, or both." (PMID 20953435, 2011). "However, GHD may contribute to the development of diabetes in diet-induced obese subjects by limiting insulin output." (PMID 21283519, 2011). "We did not demonstrate an association between sleep and diabetes control in our analysis even with adjustment for age or insulin use This may be a result of insufficient power to detect this effect." (PMID 22164161, 2011). "Therefore, increased insulin sensitivity in the homozygous patients may actually be protective with regard to the consequences (diabetes) of reduced β–cell function." (PMID 21738662, 2011). "In addition, the recognized role of chromium (III) in glucose homeostasis has lead to the investigation of chromium (III) complexes, especially oligosaccharides-chromium (III) complexes, for use as insulin-enhancing approaches for the treatment of type 2 diabetes mellitus." (PMID 21935427, 2011). "Obesity and type 2 diabetes mellitus is correlated with each other, in our experiment significant hyperglycaemia occurred due to HFD, which resulted from free fatty acid release from adipose tissue causing peripheral and hepatic insulin resistance initiating T2DM." (PMID 21235803, 2011). "In addition, it was observed that infection was a more common cause of death only in insulin-treated diabetics compared with patients without diabetes mellitus." (PMID 22082355, 2011). "The patient's diabetes was poorly controlled, with neutral protamine Hagedorn insulin measurements of 40 IU in the morning and 15 IU in the evening, and glycosylated hemoglobin levels >8%, which required adjustments of his insulin dose and addition of on-demand fast-acting insulin." (PMID 21496286, 2011). "Therefore, we hypothesized that restoration of retinal insulin signaling and glycemic normalization would exert differential effects on retinal cell survival and retinal physiology during diabetes." (PMID 22046295, 2011). "Type I diabetes mellitus (DM) results in a cell-mediated autoimmune attack against insulin-secreting pancreatic β-cells." (PMID 21241480, 2011). "Similarly, Nelfinavir is predicted to inhibit IGF-1R, which regulates the insulin/insulin-like growth factor signaling pathway, and offers one possible explanation for the observed side effects of Nelfinavir on insulin resistance and diabetes." (PMID 21552547, 2011). "Inflammation may promote development of diabetes by triggering beta cell dysfunction, apoptosis and impaired insulin signaling or development of hypertension by influencing platelet adhesion and aggregation, production of oxidants and induction of renal vasoconstriction." (PMID 21989115, 2011). "In addition, insulin down-regulates IGF binding proteins which may contribute to sex-steroid dependent cancers in diabetes, particularly postmenopausal breast and endometrial malignancies." (PMID 21773024, 2011).